COPB2-DT (COPB2 divergent transcript)
Synonyms: RP11-319G6.1
Gene: Long non-coding RNA gene on chromosome 3 (139,389,705 to 139,782,699, forward strand). Ensembl gene ENSG00000248932.
Gene Ontology:
Biological process: SRP-dependent cotranslational protein targeting to membrane, signal sequence recognition
Cellular component: signal recognition particle, endoplasmic reticulum targeting